HSF1 (heat shock transcription factor 1)
Diseases named in the same sentence as HSF1 in open-access papers (continued):
Sharing a sentence is not in itself a finding about the gene and the disease.
cancer (continued). "Next, we examined the co-amplification and co-expression of EXOSC4 with HSF1, MYC, and POU5F1B, which are located on chromosomes 8q24.3, 8q24.21, and 8q24.21, respectively, in nine different cancer types." (PMID 35008922, 2022). "The lack of effectiveness of this type of Hsp90 inhibitor is due to, inter alia, triggering a survival mechanism in cancer cells, referred to as heat shock response (HSR), driving heat shock factor 1 (HSF-1) activation." (PMID 36009046, 2022). "Under this circumstance, Mendillo and his colleagues tried to acquire more information about the relationship between HSF1 and HSF2 in cancer." (PMID 36430241, 2022). "Human cancers almost invariably overexpress main constituents of HSR, including individual HSPs and HSF1." (PMID 35311075, 2022). "The evidence that increased expression of both HSF1 and HSF2 have critically important roles in cancer development and progression has been accumulating year after year." (PMID 36430241, 2022). "Heat shock transcription factor 1 (HSF1), a central regulator of the stress response, has emerged as an important target in cancer therapy." (PMID 36245043, 2022). "We observed that rh-TSP-4 treatment increased the proliferation, invasion, EMT as well as elevated cancer stem-like features of GBC-SD and NOZ cells, while the rh-TSP-4-mediated induction of these effects were abolished by HSF1 silencing." (PMID 33407730, 2021). "Changes in mitochondrial structure resulted in activation of an OxSR through HSF-1 and NRF2, which results in increased stress resistance and survival in human cancer cells." (PMID 34714674, 2021). "Thus, HSF1 may help cancer cells overcome aberrant mitosis and its cellular consequences." (PMID 34922589, 2021). "In the cancer cell, HSP high levels are reinforced by HSF1 hyperactivation, which aids in invasion and metastasis." (PMID 34199460, 2021). "Therefore, cancer therapies that decrease the amount of estrogen a patient produces may have a different effect on estrogen receptor-positive tumors with high HSF1 levels than tumors with low HSF1 levels." (PMID 34783649, 2021). "In agreement with the notion that HSF1 is involved in EMT, the former was shown to confer drug resistance to cancer cells." (PMID 34198675, 2021). "The heat shock protein of 70 kDa (HSP70) and its transcription factor heat shock factor 1 (HSF1) play a role in mediating the survival and progression of CLL, as well as taking part in drug resistance in various cancers." (PMID 34771616, 2021). "We found that HSF1 significantly correlated with the infiltration levels of B cells, CD8+ T cells, CD4+ T cells, macrophages, neutrophils, and DCs in many cancers." (PMID 34239690, 2021). "Expression of Smac is also altered in many cancer types (reviewed), including PDAC, where downregulation is mediated by heat-shock transcription factor 1 (HSF1)." (PMID 34572737, 2021). "Nevertheless, a small molecule compound screening approach was recently shown to yield the HSF1 inhibitory compound IHSF1115, which directly interacts with the HSF1 DBD and is cytotoxic to cultured cancer cells." (PMID 32331382, 2020). "This review focuses on the expression patterns and functions of HSF1, HSF2, and HSF4 in specific cancer types, highlighting the mechanisms by which the regulatory functions of these transcription factors are modulated." (PMID 32408596, 2020). "In this study, chemotherapeutic agent (paclitaxel or doxorubicin)-resistant cancer cells showed high expression of MDR1 and increased protein stability of HSF1, which were related to the paclitaxel-mediated resistance." (PMID 32457290, 2020). "For a long time in the past, researchers have agreed that the main biological function of HSF1 is to specifically turn on downstream HSP expression and then promote cancer cells to maintain a stable state of cellular proteins." (PMID 32110802, 2020).
cancer (continued). "Overexpression of transcription factors YY1, HSF1 and SP1, known to regulate Ub gene expression, is a predictor of poor prognosis and shorter survival in several cancers." (PMID 32751694, 2020). "Apart from HSF1, recent studies have identified HSF2 as an important regulator of gene networks that affects cancer progression and survival." (PMID 32408596, 2020). "To examine the relevance of our findings to human cancer, we performed immunohistochemical (IHC) staining of human CAC patient samples with antibodies for HSF1." (PMID 33288768, 2020). "HSF1 is therefore generally considered the most robust regulator of HSP expression and the major mediator of increased HSPs in cancer." (PMID 32331382, 2020). "In this review, we focus on the expression patterns and functions of HSF1, HSF2, and HSF4 in specific cancer types and on the key mechanisms regulating HSF-driven tumor progression." (PMID 32408596, 2020). "The importance of the HSR is underscored by the existence of more than five HSF paralogs in humans, although only HSF1, HSF2, and HSF4 have been reported in the cancer literature." (PMID 32331382, 2020). "Heat shock factor 1 (HSF1) is the master regulator of the proteotoxic stress response (PSR) in all eukaryotes and cancer cells." (PMID 32110802, 2020). "Compounds shown to inhibit HSF1 activity, such as NZ28, were found to increase the radiosensitivity of cultured cancer cell lines, an effect that was augmented upon co-treatment with the HSP90 inhibitor NVP-AUY922 or 17AAG." (PMID 32331382, 2020). "Here, we assessed the role of HSF1 expression in relation to copy number alteration (CNA) and cancer prognosis." (PMID 31699156, 2019). "Overall, these data supported a model where HSF1 in CAFs leads to DKK3 upregulation, which in turn potentiates YAP/TAZ activity leading to increased ECM remodelling and promotion of cancer cell growth and invasion." (PMID 30631061, 2019). "Accumulation of molecular chaperones induced via HSF1 attributes to increases in folding demand in cancer, or to the evolution of new mechanisms for induction of HSR in quickly adapting cancer cells." (PMID 30796345, 2019). "Family with sequence similarity three member C (FAM3C) (interleukin‐like EMT inducer [ILEI]), heat shock factor 1 (HSF1) and Ying‐Yang 1 (YY1) have been independently reported to be involved in the pathogenesis of various cancers." (PMID 30887707, 2019). "The knockout of HSF-1 impairs carcinogenesis and progression, suggesting that HSF-1 is a promising and potential therapeutic target in several cancers." (PMID 29682483, 2018). "Several reports show that HSF-1 regulates MDR-1 expression at the transcriptional level and confers MDR of cancer cells against various chemotherapeutic agents." (PMID 29423046, 2018). "In the cancer cell, the increased levels of HSP is reinforced by a hyperactivation of HSF1, which itself helps promote invasion and metastasis." (PMID 28914774, 2017). "We will discuss what is known of the mechanisms of HSF1 regulation in regard to the HSP dysregulation seen in in AD and cancer." (PMID 28484363, 2017). "Overall, these results provide evidence that oridonin activates HSF1 and its downstream chaperone-mediated proteolysis pathway, which in turn is required for the degradation of BCR-ABL and the anti-cancer efficacy of oridonin." (PMID 28128329, 2017). "Inhibition of HSF1 impairs mitogenic (MAPK) signaling and contributes to inducing apoptosis in cancer cells." (PMID 27875990, 2016). "The ability of HSF1 to promote tumor development is critically dependent on its ability to upregulate HSF1 target genes, including the HSP family of genes, which facilitate the survival of cancer cells and their adaptation to hostile conditions." (PMID 26754925, 2016). "To evaluate HSF1 and HSP70 induction in three cancer cell lines following CA and/or IR treatment, we confirmed the expression levels of these proteins using Western blotting." (PMID 26029925, 2015).
cancer (continued). "Activation of HSF1 also induces expression of MDR1 gene and induces a MDR phenotype that allows escape of cancer cells from chemotherapy-mediated cell killing." (PMID 26416354, 2015). "In conclusion, we identified a novel function of HSF1 as an inhibitor of NHEJ repair through inhibition of heterodimerization of Ku70 and Ku86, which affects genomic instability and cancer development." (PMID 26359349, 2015). "Consistent with the upregulation of HSPs in cancer cells and CLL, both cultured and primary CLL B cells showed increased expression of HSF1 and the heat shock proteins HSP90, HSP70 and HSP40 compared to normal B cells." (PMID 26397138, 2015). "Thus, a single APC mutant may induce an Hsf1 program that anticipates cancer." (PMID 26320184, 2015). "Given the importance of HSF1 in cancer cell physiology, it will be interesting to see whether loss of other tumor suppressor genes, especially those leading to MAPK/PI3K pathway activation, could trigger transcriptional activity of HSF1 in different tumor types." (PMID 25954247, 2015). "HSF1 protein was detected in 124 of 134 ESCC cases (92.54 %), including 128 cases (95.52 %) in cancer cell nests and 124 cases (92.54 %) in cancer stroma." (PMID 26511079, 2015). "In the present study, we were interested to analyze the effects of HSF1 activation (Hsp90 inhibitor NVP-AUY922) and inhibition (NZ28, HSF1 knockdown) in different human cancer cells on the NK cell ligands MICA/B and its consequences on NK cell-mediated lysis." (PMID 25854583, 2015). "Therefore, it was concluded that HSF1 may support migration of cancer cells and metastasis." (PMID 24467529, 2014). "HSF1 knockdown combined with HSP90 inhibition facilitates the degradation of oncogenic proteins, induces cancer cell apoptosis, and decreases activity of the ERK pathway." (PMID 23615731, 2013). "Trastuzumab inhibited glycolysis via downregulation of heat shock factor 1 (HSF1) and LDH-A in ErbB2-positive cancer cells, resulting in tumor growth inhibition." (PMID 22844340, 2012). "Some of these genes have been previously identified as playing a role in tumorigenesis or cancer progression including, WHSC1L1, CLTC, HSF1, and LSM1." (PMID 22719901, 2012). "Since cancer cells are under constant proteotoxic stress, their negative feedback loop is already partially diminished and thus, HSF1 is hyperactivated as a chronic condition." (PMID 40204953, 2025). "The effect of HSF1 on adhesion genes is not restricted to only cancer cells, as HSF1 operates in a similar manner in CAFs." (PMID 40457168, 2025). "Additionally, 8 upstream regulatory proteins were predicted to be activated, including Rab-like protein 6 (RABL6), heat shock factor 1 (HSF1), epidermal growth factor (EGF), and ERBB2, all of which are involved in the progression of various cancers." (PMID 40301999, 2025). "The roles of HSF1 and HSF2 in cancer have been explored more in depth in other reviews." (PMID 40457168, 2025). "In addition to the extensive involvement of HSF1 in cancer, both HSF2 and HSF4 have been shown to affect cancer cell proliferation and invasion, and altered expression of HSF5 is associated with several cancer types." (PMID 40457168, 2025). "Similarly, HSF1 promotes expression of pyruvate dehydrogenase kinase 3 (PDK3), which enhances glycolysis and analogically supports cancer progression and resistance." (PMID 40287736, 2025). "Recognized as a master regulator in the process of stress response, HSF1 and its signaling were also found to be significantly correlated with MHC-I machinery activation, tumor infiltrating T cells and check point blockade response in cancer patients." (PMID 39350280, 2024). "Therefore, CDK9 inhibition in combination with HSP90 inhibition will prevent protective HSF1-mediated HSR and cell survival in cancer cells." (PMID 38326887, 2024).
cancer (continued). "Consequently, by affecting the ANXA11 promoter, LINC00857 promotes the activation of the HSF1/LINC00857/ANXA11 signalling axis, which enhances the proliferation and spread of cancer cells." (PMID 39690143, 2024). "In the present study, we show that HSF1-activating effect and the reduction of cell sensitivity to anti-cancer drugs was independent of the type of monocytic cells or tumor cell line, suggesting that the phenomenon of acquired resistance is related to HSF1." (PMID 38280079, 2024). "Given that the expression of HSF1 and its target genes participating in HSR is increased in USP7i-resistant cancer cells, we hypothesized that the USP7i-induced phosphorylation and activation of HSF1 lead to resistance to USP7i-based chemotherapy." (PMID 38474017, 2024). "BAG3, a member of the co-chaperone family, is a well-known non-HSP substrate of HSF1 and contributes to chemoresistance in cancer." (PMID 39850800, 2024). "Inhibition of HSF1 and PERK significantly sensitized cancer cells to USP7i-induced cytotoxicity." (PMID 38474017, 2024). "Due to HSF1’s ability to promote cell survival in stressful conditions, such as those faced by cancer cells during their growth, it is not surprising that HSF1 suppression is highly detrimental to tumor cells." (PMID 39243039, 2024). "HSF1 influences apoptosis and chemoresistance through its interactions with co-chaperones like BAG3 and BAG1 and it promotes cell survival by upregulating pro-survival BCL-2 family proteins and HSPs across various cancer types." (PMID 39850800, 2024). "HSF1, through its regulation of HSPs and interaction with SIRT1, contributes to 17-allylamino-17-demethoxygeldanamycin (17-AAG)-mediated chemoresistance in cancer stem-like cells by stabilizing key proteins and enhancing MDR1 drug efflux mechanisms." (PMID 39850800, 2024). "Therefore, decreasing HSF1 expression to lower HSP70 and its interaction with HOP would decrease cancer progression and thus make HSF1 a promising target for chemotherapy." (PMID 39433125, 2024). "Because of HSF1’s role in promoting HSP70 and HSP90 refolding chaperone activity, inhibiting HSF1 would likely shift the preference of HSP70 and HSP90 towards CHIP and substrate degradation, thus providing a promising cancer treatment strategy." (PMID 39433125, 2024). "Intriguingly, activation of HSF1 by mitochondrial stress in mammalian cells is also independent of hyper-phosphorylation, while PP2A mediated dephosphorylation enhances HSF1 activity in cancer cells." (PMID 38164224, 2023). "Even under non-stress settings, many cancer cells have a heightened and constitutive activation of HSF1." (PMID 37958341, 2023). "HSF1 inhibition, which was originally intended to be an anti-cancer modality, should not be toxic to normal cells." (PMID 37153737, 2023). "Accumulating evidence clearly indicates that high HSF1 levels effectively maintain protein stability in the hypermetabolic environment of tumor cells, and cancer cells have also been described as having a "nononcogenic" dependence on HSF1." (PMID 37351671, 2023). "Heat-shock family genes involved in HSF1 transactivation (e.g. HSPA1A, DNAJB1 and HSP90AB1) were also significantly enriched in this module, which has been shown previously to regulate cancer-mediated fibroblast activation." (PMID 36720863, 2023). "Given the recent findings that the interaction between HSF1 and HSF2 is essential for cancer gene expression 24, 129, an important role of HSF2 in cancer development may become increasingly significant." (PMID 37153737, 2023). "In cancer cells, heat shock treatment (43 °C for 2 h) leads to a rapid increase in HSF1 binding to HSP promoters; then, HSP gene transcription increases sharply when the state of HSF1 in tumor cells is constitutively activated." (PMID 37686660, 2023).
cancer (continued). "We initially investigated recently reported single-cell RNA sequencing (sc-RNAseq) datasets across a few different cancers and queried whether DYRK2 and HSF1 expression overlapped between the heterogenous cell populations within diverse tumours." (PMID 36622366, 2023). "Hence, we evaluated furtherly the effects of targeting HSF1-APOJ-STAT3 axis on CD8+ T cells-mediated cancer cells cytotoxicity and verified the enhancement of CD8+ T cells-mediated cytotoxicity when HSF1-APOJ-STAT3 axis was inhibited in HCC cells." (PMID 36482717, 2023). "HSF1 was also identified through a pooled RNA interference screen, and the combination of HSF1 knockdown with HSP90 inhibitors exhibited a marked effect on various cancer cell lines and tumor mouse models." (PMID 36139353, 2022). "HSF1 itself is not tumorigenic but its depletion restricts growth of diverse cancer lines while having little effect on normal cells." (PMID 35311075, 2022). "Although HSF1 is not an oncogene, it enables cancer cells to accommodate imbalances in signaling and alterations in DNA, protein, and energy metabolism, a phenomenon called “non-oncogene addiction”18,24,27–29." (PMID 36245043, 2022). "A lack of HSF1 has been shown to dramatically deplete HIF1A and decrease angiogenesis, which is directly linked to a cancer cell’s growth and development." (PMID 36347941, 2022). "Increased HSF1 can act a rule as a transcription factor and cause evaluate the expression of lactate dehydrogenase A (LDHA), and oppositely reducing HSF1 can decrease the expression of LDHA, which targets one of the vital processes of cancer cells, which is actually glycolysis." (PMID 35990198, 2022). "In particular, the expression of FOS, FOSB, and ATF3 did not correlate with the low HSF1 levels in these cancer types." (PMID 36010586, 2022). "Although depletion of this transcription factor sensitized cancer cells to anoikis, HSF1 activation in normal bronchial epithelium did not confer the ability of anchorage-independent growth." (PMID 35311075, 2022). "They showed that knockdown of HSF1 strongly inhibited the survival of various cancer cells, whereas WI-38 normal fibroblast cells were not affected." (PMID 36430241, 2022). "Finally, overexpression and activation of heat shock transcription factor 1 (HSF1), which is observed in cancer cells, can be related to increased satellite DNA expression." (PMID 35885937, 2022). "On the other hand, JUN, JUND, and FOSL1, another set of potential targets of HSF1 upregulated after heat shock, were expressed at higher levels (or not significantly changed) in all analyzed HSF1high cancers." (PMID 36010586, 2022). "Normal breast tissue typically shows no nuclear HSF1 staining, whereas HSF1 was commonly detectable in cancers, most abundantly in high-grade carcinoma." (PMID 35311075, 2022). "We found that HSF1 was co-amplified and co-expressed with EXOSC4 in all nine cancer types." (PMID 35008922, 2022). "The analysis revealed the highest upregulation of PGR and LINC01016 genes in ER+ compared to ER− cancers (regardless of HSF1 status)." (PMID 34783649, 2021). "The upregulated expression of HSF1 correlated with worse OS, DSS, DFI, or PFI in several cancers." (PMID 34239690, 2021). "The upregulation of the HSF1 expression corresponded to a poor prognosis in patients and correlated with the infiltration levels of B cells, CD8+ T cells, CD4+ T cells, macrophages, neutrophils, and DCs in diverse cancers." (PMID 34239690, 2021). "Interestingly, HSF1, HIF1α, RXR, and VDR have been described as CAF modulators in various cancer types." (PMID 33670717, 2021). "Although high HSF1 levels slightly reduced the survival in ER+ cancer patients, they had a greater negative outcome on survival in ER-negative patients." (PMID 34783649, 2021). "Emerging evidence revealed the significant roles of heat shock factor 1 (HSF1) in cancer initiation, development, and progression, but there is no pan-cancer analysis of HSF1." (PMID 34239690, 2021).